JAK1 (Janus kinase 1)
Diseases named in the same sentence as JAK1 in open-access papers (continued):
Sharing a sentence is not in itself a finding about the gene and the disease.
ovarian carcinoma (20 papers, 2002 to 2025). A malignant neoplasm originating from the surface ovarian epithelium. "An in vitro study with one endometrial cancer and two ovarian cancer cell lines harboring JAK1 frameshift mutations demonstrated that JAK1 mutations impede STAT1 posphorylation and upregulation of antigen presenting machinery components LMP2 and TAP1." (PMID 27213585, 2016). "The JAK1/STAT3 pathway has been studied extensively in ovarian cancer in multiple models, identifying this pathway as a potential target." (PMID 40806640, 2025). "In this study, we investigated the therapeutic potential of the JAK1/JAK2 inhibitor ruxolitinib in ovarian cancer treatment, either alone or in combination with conventional chemotherapy agents." (PMID 29849942, 2018). "Some target genes, such as BAX, are altered in diverse MSI tumor types (e.g. colorectal- and ovarian cancer), whereas others, such as JAK1, have a very restricted occurrence in MSI endometrial cancers." (PMID 27213585, 2016). "We here examined the sensitivity of ovarian cancer cells to gefitinib when the JAK/STAT3 pathway was depleted either with JAK1 siRNA or STAT3 siRNA." (PMID 25928246, 2015). "Our previous study has demonstrated that the constitutive phosphorylation of STAT3 is largely mediated through JAK1 in these ovarian cancer cells, suggesting a possibility of JAK1 as a main kinase responsible for activation of STAT3 by EGF blockade." (PMID 25928246, 2015). "Immunohistochemistry for JAK1, STAT1, and STAT3 was performed on samples of patients with ovarian cancer to confirm the correlation between JAK-STAT family expression and platinum treatment response." (PMID 40883550, 2025). "Through integrated network analysis and clinical transcriptomic data, we identified five core targets (EGFR, JAK1, JAK2, PTPN11, and SRD5A1) that are differentially expressed in ovarian cancer tissues and serve as central nodes in TWP’s mechanism of action." (PMID 41181611, 2025). "Our investigation revealed that TWP’s efficacy is driven by its ability to modulate five core targets—EGFR, JAK1, JAK2, PTPN11, and SRD5A1—which our analysis showed to be dysregulated in clinical ovarian cancer datasets." (PMID 41181611, 2025). "In highly aggressive ovarian cancer cells, Gln breaks down into the TCA cycle relying on GLS and activates JAK1." (PMID 36523985, 2022). "The targeted inhibition of the JAK1/STAT3 pathway can effectively prevent the progression and metastasis of ovarian cancer." (PMID 35991559, 2022). "In the CSCs sorted from human ovarian cancer SKOV3 and A2780 cell lines, OCT4 can promote tumorigenesis by increasing the phosphorylation levels of JAK1 and STAT6 proteins of JAK/STAT signaling pathway." (PMID 34628473, 2021). "Three PTKs, janus kinase 1, insulin-like growth factor 1 receptor, and discoidin domain receptor 1 (DDR1), were identified and only DDR1 was overexpressed in all ovarian cancer tissues examined for the validation by quantitative real-time PCR." (PMID 21541037, 2011). "It has also been used to detect complex CNVs such as JAK1-PAK2, JAK1-PVT1, JAK1-MYOCD, JAK1-TIMM21, USP7-TIMM21, and JAK1-Chr22 CNVs in whole blood-derived ovarian cancer samples, EGFR, CDKN2A, and BRAF CNV in glioma tissues, as well as FGFR2 CNV in colorectal and gastric adenocarcinomas." (PMID 40725150, 2025). "ERK1/2 and Janus-activated kinase 1 (JAK1) affect cancer cell proliferation, metabolic regulation, and cancer cell metastasis through the regulation of STAT3 amino acid phosphorylation levels in invasive ovarian cancer cells." (PMID 36523985, 2022). "Targeting JAK1/STAT3, therefore, could be a potential novel therapeutic approach for treating advanced and chemoresistant ovarian cancer." (PMID 29849942, 2018). "The DDR1 gene was overexpressed in all eight individuals, whereas the expression levels of JAK1 and IGF1-R were not increased in half of the ovarian cancer tissue samples." (PMID 21541037, 2011).
pancreatic cancer (19 papers, 2016 to 2025). "This group also reported that dMMR tumors were less likely to have mutations in traditional pancreatic cancer markers such as KRAS and SMAD4, but rather showed mutations in JAK1 and ACV2RA which correspond with microsatellite instability." (PMID 39458133, 2024). "However, one phase II clinical trial evaluated ruxolitinib, a selective JAK1/2 inhibitor, for pancreatic cancer therapy (NCT01423604)." (PMID 33546207, 2021). "Given that activation of the JAK1 and JAK2 pathways has been demonstrated to inhibit tumour cell susceptibility to NK cells by upregulating PD-L1 expression 39, we further investigated the activation status of the JAK-STAT pathway in RBM10-knockdown pancreatic cancer cells." (PMID 40740233, 2025). "Our results confirmed that the expression of phosphorylated JAK1 (P-JAK1), phosphorylated JAK2 (P-JAK2), and phosphorylated STAT3 (P-STAT3) was upregulated in pancreatic cancer cells following RBM10 knockdown." (PMID 40740233, 2025). "Four JAK and seven STAT family members have been described in humans, although significant elevations in expression and activation of JAK1/2 and STAT3, in particular, have been observed in pancreatic cancer patients." (PMID 33546207, 2021). "Ruxolitinib (a specific JAK1/JAK2 inhibitor) was highlighted here based on its use in current phase 1, 2, and 3 clinical trials against pancreatic cancer (trials NCT01423604, NCT02117479, NCT02119663, and NCT01822756)." (PMID 27533247, 2016). "Consistently, deletion of RAGE expression in pancreatic cancer cells leads to downregulated IL-6 expression, STAT3 localization to mitochondria, as well as the downregulation of the upstream signaling pathways such as phosphorylation of Jak1 and Src." (PMID 29474476, 2018).
acute lymphoblastic leukemia (17 papers, 2013 to 2025). Leukemia with an acute onset, characterized by the presence of lymphoblasts in the bone marrow and the peripheral blood. "The predicted base edited variant, Arg724His, has been implicated in activating JAK1 signaling in acute lymphoblastic leukemia through dysregulating intramolecular inhibition of the kinase domain." (PMID 36669486, 2023). "Homologous mutation to JAK2 V617F in JAK1 (V658F) causes acute lymphoblastic leukemia." (PMID 31892268, 2019). "CRLF2 rearrangements occur in >50% of Ph-like and Down syndrome (DS)-associated B-acute lymphoblastic leukemia (ALL) and induce constitutive kinase signaling targetable by the JAK1/2 inhibitor ruxolitinib under current clinical investigation." (PMID 39681640, 2025). "Sustained activation of the JAK-STAT signaling pathway is a key driver in the initiation and progression of T-cell acute lymphoblastic leukemia (T-ALL), with activating mutations in JAK1 (e.g., V658F) and JAK3 (e.g., M511I) commonly reported in T-ALL cases." (PMID 41438753, 2025). "For example, a suite of mutations that increase the flux through the IL-7R/JAK1/JAK3/STAT5 pathway have been reported in acute lymphoblastic leukemia (ALL)." (PMID 38254802, 2024). "In particular, somatic GOF mutations in JAK1 have been described in oncological pathologies such as acute lymphoblastic leukemia (ALL), acute myeloid leukemia (AML), and solid-organ cancers." (PMID 37140667, 2023). "The corresponding somatic JAK1 JH2 mutations (V658I or V658F) are present in patients with acute lymphoblastic leukemia (ALL), T-cell prolymphocytic leukemia (T-PLL), and myeloid malignancies." (PMID 34073410, 2021). "Accordingly, somatic JAK1 GOF mutations are found in 10–20% of T-cell acute lymphoblastic leukemia (T-ALL) patients." (PMID 31892268, 2019). "JAK1 somatic mutations occur in individuals with acute lymphoblastic leukemia (ALL)." (PMID 31831954, 2019). "Additionally, it has been reported that somatic mutations in JAK1 occurred in individuals with acute lymphoblastic leukemia (ALL) and the dysregulated JAK1 function effected on ALL, particularly of T cell origin." (PMID 27903959, 2017). "Recent studies of acute lymphoblastic leukemia have identified activating mutations in components of the interleukin-7 receptor complex (IL7R, JAK1, and JAK3)." (PMID 26208852, 2015). "For example, the importance of JAK/STAT in early T-cell precursor (ETP) acute lymphoblastic leukemia (ALL) has been confirmed when the JAK1/2 inhibitor ruxolitinib has been used in murine xenograft models leading to abrogation of the STAT5 activation in response to IL-7." (PMID 34055801, 2021). "In contrast, PTPN2 is likely a tumor suppressor in acute lymphoblastic leukemia (ALL) because it inhibits JAK1, which is oncogenic in ALL, though PTPN2 levels are often low in ALL." (PMID 35911672, 2022).
asthma (17 papers, 2018 to 2025). "It exhibits broad inhibition of signalling induced by JAK1-dependent cytokines associated with the entire spectrum of inflammatory phenotypes observed in asthma." (PMID 40604958, 2025). "While CXCL1, CXCL2, and CXCL5 gene transcripts were shown to be elevated in a mouse model of severe asthma, treatment with Ruxolitinib, an anti-inflammatory drug and powerful inhibitor of janus kinase 1/2 (JAK1/2), caused the upward spiraling to be reversed." (PMID 36164329, 2022). "Our results show, for the first time, that such anti-asthma effects may be associated with reduction of the IL-4/JAK1/STAT6 pathway." (PMID 30172259, 2018). "Londamocitinib (AZD4604) is a highly selective Janus kinase 1 (JAK1) inhibitor that is being developed as a novel inhaled therapy in patients with uncontrolled asthma despite ICS use." (PMID 40604958, 2025). "ARTEMISIA will evaluate the effect of londamocitinib, a novel JAK-1 inhibitor, on gene expression in the airways of a broad population of uncontrolled, moderate-to-severe asthma with varying degrees of T2 inflammation." (PMID 40604958, 2025). "They found that CD4+ T cells were predominant cell type in severe asthma, and exhibited a pro-inflammatory signature of increased JAK1 expression." (PMID 36524132, 2022). "We have demonstrated that JAK1 is a possible therapeutic target for severe corticosteroid‐resistant asthma with airway eosinophilia and persistent Th2‐type inflammation, and that ruxolitinib has potential as an alternative pharmacotherapy." (PMID 33534941, 2021). "JAK1 inhibitor is sufficient to suppress asthma-related inflammation and lung pathology in OVA-induced animal models." (PMID 34194525, 2021). "Western blot analysis results of lung tissues showed that in Tespa1−/− asthma mice, the phosphorylation level of JAK1 increased, but the increase in P-JAK2 level was negligible, indicating that Tespa1 mainly regulates the IL-4/JAK1 signaling pathway." (PMID 33228696, 2020). "Whilst the participants taking part in ARTEMISIA all have asthma, insights gained from this study may inform future work assessing the utility of JAK1 inhibition in other respiratory diseases." (PMID 40604958, 2025). "The suppressive effect of AG on JAK1/STAT3 signaling pathway by regulating Th17 cells may have the potential for treating asthma or other inflammation-mediated diseases." (PMID 34194525, 2021). "Although the composition of the cell subsets was similar between the groups, increased expression of JAK1, the long noncoding RNA NEAT1, and IL32 was noted in specific cell types of patients with severe asthma." (PMID 39672815, 2024). "TGF-, IL-1, IL-4 (JAK1/3-STAT3/5/6), IL-5 (JAK2-STAT3), IL-6, and IL-13 (JAK1) are JAK-STAT pathway activators in asthma." (PMID 35054524, 2022). "Neutrophils from healthy subjects, severe asthma and COPD patients showed a higher expression of JAK2 followed by JAK3 and in a lesser extent of JAK1, while levels of TYK2 were the lowest." (PMID 35332239, 2022). "We conclude that AG inhibits the inflammatory response of asthma in OVA-stimulated mice by blocking the activation of Th17-regulated cytokines and the JAK1/STAT3 signaling pathway." (PMID 34194525, 2021). "The top 10 highest degree of targets were EGFR, JAK1/2, MAPK14, VEGF, SRC, mTOR, PI3K, and GSK3B, which might be the critical targets of HHAE for the treatment of asthma." (PMID 36408342, 2022). "The observed increase of JAK1 expression in unstimulated cells, combined with a prominent role for STAT1 in steroid and poly I:C responses, suggests that the JAK1-STAT1 pathway holds clues to the complex interaction between asthma, therapeutic response to steroids, and antiviral responses." (PMID 33902571, 2021).
asthma (continued). "In addition to finding increased expression of JAK1 in unstimulated cells of SA, we found high expression of pro-inflammatory genes including IL32, a cytokine with pro-inflammatory and antiviral activity; genes involved in Th2 inflammation; and CCL4, involved in asthma exacerbations." (PMID 33902571, 2021).
endometrial cancer (17 papers, 2016 to 2026). Primary or metastatic malignant neoplasm involving the endometrium (mucous membrane that lines the endometrial cavity). "Recurrent JAK1 frameshift mutations occurred at the highest frequency in endometrial cancers, but were also found in prostate, urinary, gastric, and colon cancers." (PMID 29121062, 2017). "In parallel, Kim and colleagues found 30% of endometrial cancer in TCGA were microsatellite instability-high (MSI-H) and 30% of TCGA MSI-H endometrial cancer cases had JAK1 frame-shift truncating mutations." (PMID 28977839, 2017). "Two patient cohorts derived from the PORTEC-1 and -2 randomized trials with MSI early-stage endometrial cancers (n=198) with long-term mature follow-up data were used to investigate a possible prognostic effect of JAK1 frameshift mutations." (PMID 27213585, 2016). "Twenty-two (35%) MSI endometrial cancers had a JAK1 frameshift mutation, mainly at position K860, whereas only 3 of 110 (3%) MSS endometrial cancers had a JAK1 mutation (P<0.001)." (PMID 27213585, 2016). "The high rate of JAK1 mutations in MSI endometrial cancer is suggestive of an adaptation favoring tumor survival by blocking the JAK/STAT pathway activity, and impeding an adequate immune response." (PMID 27213585, 2016). "The overall JAK1 mutation frequency of 28% in our large series of MSI endometrial cancers is in line with findings from two recent smaller studies." (PMID 27213585, 2016). "Altogether, the occurrence of JAK1 mutation specifically in endometrial cancer is suggestive of a positive selection for this mutation in endometrial cancer." (PMID 27213585, 2016). "We have identified a high frequency of JAK1 mutations in MSI endometrial cancers in two relatively large series of MSI endometrial cancers." (PMID 27213585, 2016). "JAK1 loss-of-function (LOF) mutations have been found in endometrial cancer and may facilitate immune evasion." (PMID 36376931, 2022). "Finally, the effect of JAK1 mutation status on survival was evaluated in a large independent cohort of 198 MSI endometrial cancer patients with mature long-term follow-up from the PORTEC-1 and -2 clinical trials." (PMID 27213585, 2016). "In this independent cohort, fifty-two (28%) of MSI endometrial cancers had a JAK1 mutation." (PMID 27213585, 2016). "MSI endometrial cancers show a remarkably high number of JAK1 frameshift mutations that may have clinical implications." (PMID 27213585, 2016). "JAK1 mutations in MSI endometrial cancers may interfere with the T-cell response due to impaired HLA class I or PD-L1 expression." (PMID 27213585, 2016). "JAK1 frameshift mutations may promote cancer cell immune evasion by impeding upregulation of the antigen presentation pathway in microsatellite unstable endometrial cancers (ECs)." (PMID 27213585, 2016). "In addition, the JAK1 c.[383G>A] mutation was previously identified in an endometrial carcinoma sample from the Cancer Genome Atlas (TCGA) project." (PMID 27248819, 2016). "Other studies have shown that inactivation of JAK1 promotes proliferation of endometrial cancer cells by upregulating the HIF1α signaling pathway." (PMID 41520505, 2026). "It has been found to have an antineoplastic role in endometrial cancer through effects on Jak1 and STAT3 signaling." (PMID 40686703, 2025). "Taken together, we demostrate that CD146+CAFs can promote progression of endometrial cancer by inducing angiogenesis and vasculogenic mimicry via IL-10/JAK1/STAT3 pathway." (PMID 38459564, 2024). "IL-10 promoted epithelial-endothelial transformation (EET) and further VM formation in endometrial cancer cells via the janus kinase 1/signal transducer and activator of transcription 3 (JAK1/STAT3) signalling pathway." (PMID 38459564, 2024). "We also showed that CD146+CAFs promoted the progression of endometrial cancer by inducing angiogenesis and VM via the IL-10/JAK1/STAT3 pathway in vitro and in vivo exploration." (PMID 38459564, 2024).